ZNF280C (zinc finger protein 280C)
Description:
May function as a transcription factor.
Synonyms: SUHW3; ZNF633; FLJ20095; ZPET
Tractability: PROTAC: UniProt records ubiquitination sites on it; ubiquitination databases record sites on it; its protein half-life has been measured.
Gene: Protein-coding gene on chromosome X (130,202,707 to 130,268,899, reverse strand). Ensembl gene ENSG00000056277.
Subcellular location: Nucleus
Subcellular location (Human Protein Atlas): Nucleoli fibrillar center; Nucleoplasm
Gene Ontology:
Molecular function: protein binding; DNA-binding transcription factor activity, RNA polymerase II-specific; RNA polymerase II cis-regulatory region sequence-specific DNA binding
Biological process: regulation of DNA-templated transcription; regulation of transcription by RNA polymerase II
Cellular component: nucleus
Homologues: Orthologues: chimpanzee ZNF280C (97% identical), macaque ZNF280C (96% identical), dog ZNF280C (76% identical), pig ZNF280C (76% identical), rat Zfp280c (67% identical), mouse Zfp280c (66% identical), guinea pig ZNF280C (60% identical), rabbit ZNF280C (59% identical). Paralogues in human: ZNF280D (67% identical), ZNF280B (34% identical), ZNF280A (30% identical), ZBTB49 (12% identical), ZBTB21 (11% identical), FEZF2 (10% identical), GFI1 (9% identical), FEZF1 (9% identical), PRDM13 (9% identical), ZBTB14 (8% identical), ZBTB7B (8% identical), BCL6 (7% identical), and 16 more.
Diseases named in the same sentence as ZNF280C in open-access papers:
ZNF280C is named in the same sentence as 2 diseases in open-access papers, as found by Europe PMC text mining. Sharing a sentence is not in itself a finding about the gene and the disease. The quoted sentences say what the papers report.
melanoma (1 paper, 2024). A malignant, usually aggressive tumor composed of atypical, neoplastic melanocytes. "The X‐linked cancer‐related genes that have been associated with melanoma include ZNF280C, IL3RA, PNMA3, NHS, and FGD1." (PMID 38827026, 2024).
cancer (2 papers, 2024 to 2025). A tumor composed of atypical neoplastic, often pleomorphic cells that invade other tissues. "We also identified novel TFs such as NOBOX in HNSC, ZNF280C in KIRP, and POU6F2 in LUSC, which potentially regulate cancer-specific regulatory networks yet remain relatively understudied in those cancer types." (PMID 40748712, 2025).